EGFR (epidermal growth factor receptor)
Diseases named in the same sentence as EGFR in open-access papers (continued):
Sharing a sentence is not in itself a finding about the gene and the disease.
cancer (continued). "Immunohistochemical (IHC) analysis of 226 LUAD specimens showed that TTF-1-negative tumors were associated with epidermal growth factor receptor wild-type status, advanced stage, and worse progression-free and cancer-specific survivals." (PMID 40824335, 2025). "The triggering of EGFR causes the activation of myofibroblasts, leads to the secretion of various factors, and causes the progression of cancer cells." (PMID 40573291, 2025). "The mutation or overexpression of Epidermal Growth Factor Receptor (EFGR) is often seen in cancers, increasing uncontrolled cell growth, making it another important antigen target in some cancers (NCT04976218)." (PMID 41476860, 2025). "In particular, EGFR mutations are commonly observed in cancer and the activation of the EGFR pathway is increased in the airway epithelium of CF patients." (PMID 40563468, 2025). "Immune checkpoint inhibitors (ICIs) have changed the paradigm of cancer treatment, but their effectiveness in some patients with epidermal growth factor receptor (EGFR) mutations is unsatisfactory." (PMID 40574864, 2025). "While circRNA dysregulation has been implicated in various cancers, the role of circ-EGFR in response to EGFR-targeted therapy in mCRC remains largely unexplored." (PMID 41214390, 2025). "It further proposes cancer-specific therapies, offering a more precise analysis for identifying EGFR-TKI resistant cells and investigating the underlying mechanisms of heterogeneity and drug resistance within tumors." (PMID 40003951, 2025). "Such mutations can result in the constitutive activation of EGFR, thereby promoting the uncontrolled proliferation of cancer cells." (PMID 39836268, 2025). "EGFR inhibitors such as gefitinib and erlotinib have shown promise in treating cancers that overexpress EGFR or express mutated EGFR." (PMID 40071065, 2025). "Abnormal stimulation of these signaling pathways, resulting from EGFR overexpression or mutation, leads to uncontrolled cell growth, proliferation, and increased cancer cell adhesion, motility, and metastasis." (PMID 40732338, 2025). "EGFR overexpression, due to gene amplification, mutations, or increased ligand expression, contributes to excessive signaling in cancer cells, making EGFR a significant target in cancer treatment." (PMID 40001513, 2025). "EGFR overexpression or mutations resulting in dysregulation of receptor signaling are found in various types of cancer, thus making EGFR a major therapeutic target and prognostic marker." (PMID 39744818, 2025). "The TKI domain of EGFR contains several regions frequently mutated in cancer, with distinct mutation patterns across different exons." (PMID 40875066, 2025). "We are currently focusing on evaluating the in vivo efficacy of BIEGi-1 and its derivatives in animal models, with an eventual goal of clinical trials for cancer patients with EGFR mutations." (PMID 40259053, 2025). "Metabolomics offers a promising avenue for identifying such biomarkers, especially considering that cancer-associated metabolic alterations—including those driven by EGFR mutations—can vary across populations." (PMID 41142757, 2025). "Altered expression of EGFR is linked to disruption of tissue homeostasis and various diseases, among which cancer." (PMID 39966897, 2025). "It has been implicated in the activation of downstream EGFR signaling, which promotes cancer cell proliferation and survival." (PMID 40507920, 2025). "The mechanistic complexity of marinopyrrole A was further underscored in cancers harboring epidermal growth factor receptor (EGFR) mutations and tumors exhibiting elevated phosphorylated AKT (p-AKT)." (PMID 41149606, 2025). "The development of resistance in cancer has also been linked to the feedback stimulation of EGFR signaling." (PMID 40056327, 2025). "Fourth-generation EGFR-TKIs have good therapeutic effects on various types of tumors and cancers with multiple mutations." (PMID 40535810, 2025).
cancer (continued). "The NGF signaling axis was associated with the sensitivity of cancer cells to EGFR inhibitors in malignant tumor." (PMID 40612670, 2025). "Dysregulation of epidermal growth factor receptor (EGFR) is one of the most common mechanisms associated with the pathogenesis of various cancers." (PMID 39129344, 2025). "Key signaling pathways, such as those involving the EGFR and associated cascades, are activated by bile acids, affecting various genes involved in cancer growth." (PMID 40102272, 2025). "Elevated CEA levels in patients with cancer-causing factors are linked to their resistance to EGFR-tyrosine kinase inhibitors (TKIs), underscoring the necessity for more treatment approaches to counteract resistance." (PMID 40712559, 2025). "One of the most frequently mutated or overexpressed RTK in cancers is the epidermal growth factor receptor (EGFR)." (PMID 39966897, 2025). "Dysregulation or mutations in EGFR contribute to cancer development, making it a target for cancer therapies, including EGFR inhibitors." (PMID 40287845, 2025). "The EGFR gene is one of the most frequently mutated genes in a variety of cancers, such as gastroesophageal adenocarcinoma, lung cancer, breast cancer, carcinoma of the bladder, rectal cancer and glioblastoma." (PMID 40368641, 2025). "NSCLC remains a leading cause of cancer-related mortality, and the emergence of resistance to EGFR-TKIs like AZD9291 significantly complicates treatment strategies." (PMID 40877231, 2025). "NGS targeting 54 cancer related genes, including assessments for copy number variants in EGFR, ERBB2, and MET." (PMID 40867329, 2025). "These mutations lead to enhanced EGFR signal transduction and promote cancer development, but the first generation of EGFR-TKIs has a significant therapeutic effect." (PMID 40172117, 2025). "Together, these data highlight the value of simultaneously targeting EGFR’s GEF and kinase activities to restrict the growth of cancer cells harboring EGFR mutations." (PMID 40259053, 2025). "The efficacy of this approach was demonstrated by successful allele-specific editing of cancer-associated heterozygous point mutations in EGFR L858R and KRAS G12V, while minimizing editing of the corresponding wild-type alleles." (PMID 41301194, 2025). "While chemotherapy is known to accelerate muscle loss in cancer patients, there is also emerging evidence in the context of EGFR-TKIs." (PMID 41425618, 2025). "Mutations in the EGFR gene can result in overproduction of the EGFR protein, causing cells to divide and expand uncontrollably, ultimately leading to cancer." (PMID 40725000, 2025). "Overall/Objective response rates (ORRs) among patients with EGFR mutation-positive cancer cells receiving gefitinib have been documented to range from 62 to 85%." (PMID 41199076, 2025). "Epidermal growth factor receptor (EGFR) plays an important role in normal epithelial cell physiology and is overexpressed or mutated in many cancers, promoting tumorigenesis." (PMID 40893150, 2025). "Research data show that the EGF gene and its receptor gene EGFR are closely associated with cancer occurrence and metastasis." (PMID 40696566, 2025). "RNA sequencing data identified USP11 upregulation in CRC tissues and found it to be associated with cancer-related gene sets, particularly those related to EGFR and TLR signaling." (PMID 41419456, 2025). "This high variation is affected by various factors such as the histopatholgical type of cancer, the presence status of the epidermal growth factor receptor (EGFR) mutation/wildtype, and the actual stage of disease." (PMID 40064706, 2025). "This phenomenon is very common and often enhanced in many human cancers due to high levels of EGFR or specific missense mutations." (PMID 40649937, 2025). "SNARE affects the internalization, trafficking, and fate of receptors, such as EGFR, which are known to be linked to cisplatin resistance pathways and alter the response of cancer cells to cisplatin-induced DNA damage." (PMID 40362252, 2025).
cancer (continued). "Overall, cancer cells with EGFR overexpression and mutation have a detrimental impact on cancer immunotherapy." (PMID 40859900, 2025). "Previous studies have shown an association between EGFR alterations and aggressive biological characteristics in different human cancers of epithelial origin." (PMID 41227364, 2025). "For instance, the resistance of MDA-MB231 (breast), A549 (lung), and Panc-1 (pancreas) cancer cells to the EGFR inhibitor erlotinib is associated with αvβ3 integrin-mediated cancer stemness." (PMID 40243917, 2025). "Mutations in the EGFR gene are frequently associated with a variety of cancers, particularly non-small cell lung cancer (NSCLC), and are key drivers of tumor progression." (PMID 40875066, 2025). "The real-time PCR primer sets developed in this study have the potential to be used as an easy method for the detection of EGFR mutation before the administration of drugs such as Cetuximab in cancer patients." (PMID 40332084, 2025). "In EGFR-mutant cancer cells, an oncogenic mutation in the catalytic subunit alpha of phosphatidylinositol-4,5-bisphosphate 3-kinase (PIK3CA) was adequate to induce resistance to gefitinib, an EGFR inhibitor." (PMID 40342734, 2025). "The use of targeted agents, such as osimertinib in this patient with an EGFR mutation, represents the evolving landscape of personalized cancer therapy." (PMID 41503294, 2025). "Such inhibitors have been successfully designed to target different mutations in the TK domain of the EGFR and have been used in the treatment of cancers such as NSCLC." (PMID 40006082, 2025). "Our aim was to develop an allele-specific CRISPR targeting strategy for pathogenic DNA sequences that contains cancer-related EGFR L858R and KRAS G12V mutations." (PMID 41301194, 2025). "In this work, the epidermal growth factor receptor (EGFR) is considered as a biomarker, the expression of which is associated with accelerated division and proliferation of cancer cells." (PMID 41473440, 2025). "The in silico docking studies identified that compound 22 is able to interact with human SIRT2 and EGFR proteins (often found to be mutated or overexpressed in various cancer cell lines) with promising antiproliferative activity." (PMID 40430551, 2025). "These interactions suggest the complex interplay between virulence factors of Candida species and host cell receptors in cancer, with EGFR, HER2, and EphA2 being receptor tyrosine kinases implicated in cancer progression." (PMID 40284554, 2025). "In NPC and other EGFR-driven cancers, compensatory MET activation has been implicated in resistance to EGFR-targeted therapies by reactivating downstream PI3K/AKT and MAPK signaling and promoting EMT." (PMID 41002550, 2025). "Socioeconomic status, EGFR mutation subtype, and disease extent at cancer diagnosis were independent predictors of treatment outcomes in that setting." (PMID 40029742, 2025). "The sustained activation of PI3K/Akt signaling brought about by PTEN loss engenders an environment in which cancer cells become less reliant on EGFR signaling for sustenance and propagation." (PMID 40129883, 2025). "Unfortunately, EGFR develops acquired resistance to targeted tyrosine kinase inhibitors (TKIs) in many cancer patients due to further mutation(s)." (PMID 40649937, 2025). "This stark contrast between CRC and other BRAF-mutated cancer types has been shown to be related to EGFR-mediated reactivation of the MAPK pathway upon inhibition of BRAF." (PMID 41294686, 2025). "Further detail is needed on the specific molecular pathways by which PM2.5 induces oxidative stress and inflammation and how these processes directly lead to EGFR mutations and cancer development." (PMID 39578555, 2025). "Signal transduction molecules, in the case of their mutations or overactivity, forms of EGFR are noticed in cancer tissues." (PMID 39561105, 2025).
cancer (continued). "In that setting, socioeconomic status, EGFR mutation subtype, and disease extent at cancer diagnosis were independent predictors of treatment outcomes." (PMID 40029742, 2025). "In conclusion, our data underscores the role of circ-EGFR in risk stratification and response prediction in mCRC patients treated with cetuximab, offering hope for more effective and personalized cancer treatments in the future." (PMID 41214390, 2025). "EGFR has been identified as a proto-oncogene that is mutationally activated in various human cancers." (PMID 40523886, 2025). "We also aim to investigate the epidemiology, risk factors, cancer progression, and clinical outcomes according to standard treatment or newly introduced treatment of EGFR‐mutated NSCLC." (PMID 39757012, 2025). "Multivariable analysis showed that shorter time-to-treatment discontinuation was independently associated with socioeconomic deprivation, EGFR L858R mutations, and distant disease at cancer diagnosis." (PMID 40029742, 2025). "The epidermal growth factor (EGF) has a well-established role in cellular proliferation, with aberrant expression and/or activating mutations of the EGF receptor (EGFR) linked to the development of several cancers." (PMID 39924511, 2025). "Dysregulation of EGFR signaling in cancer is often caused by mutations, amplifications, or overexpression, which results in increased cell proliferation, reduced apoptosis, and resistance to therapies like chemotherapy and radiation." (PMID 40938821, 2025). "Positive samples were prepared by mixing three plasma samples from cancer patients, each positive for distinct mutations: EGFR exon 19 deletion (c.2235_2249del), EGFR p.L858R (c.2573T > G), and BRAF p.V600E (c.1799T > A)." (PMID 40075630, 2025). "The twenty most significantly enriched signaling pathways encompassed those associated with cancer, the EGFR tyrosine kinase pathway, and the PI3K-Akt signaling pathway." (PMID 40864816, 2025). "EGFR plays an essential role in the normal development of the skin and its appendages, so all cancer patients receiving EGFRIs are at risk of nail changes." (PMID 40297810, 2025). "As in cancer development, the dysregulation of EGFR impairs placenta development, causing PE disorder." (PMID 39966897, 2025). "Although IGFBP7 has been identified as a cancer suppressor, in this study it was associated with resistance to three generations of EGFR TKI drugs." (PMID 40224214, 2025). "The assay was designed to detect the L858R mutation in exon 21 of the EGFR gene, a key driver mutation in various cancers." (PMID 40994682, 2025). "Aberrant EGFR signalling is closely linked to increased cancer cell aggressiveness and poorer clinical outcomes." (PMID 40265416, 2025). "Epidermal growth factor receptor (EGFR) is a key stimulator of cancer growth and is closely associated with tumorigenesis, making EGFR-TKIs a critical focus in anticancer drug development." (PMID 40861456, 2025). "By inhibiting the activity of mutated EGFR, osimertinib blocks the signalling pathways that promote cancer cell growth, division and survival." (PMID 39858093, 2025). "Similar trends were seen in northern China, where younger patients had a higher proportion of EGFR mutations, a family history of cancer, and late-stage presentation." (PMID 41322774, 2025). "Many oncogenic mutations in EGFR have been identified in cancer cells, with one of the most prevalent being the L858R point mutation in exon 21, occurring in approximately 40% of lung cancer cases." (PMID 40449599, 2025). "A kinase target in oncology where optimization of back‐pocket binding groups has been impactful is the epidermal growth factor receptor tyrosine kinase (EGFR) that is often observed mutated in diverse human cancers." (PMID 40665765, 2025).
cancer (continued). "Activating mutations in the epidermal growth factor receptor (EGFR) are key oncogenic drivers across multiple cancers, yet the structural mechanisms by which these mutations promote persistent receptor activation remain elusive." (PMID 40650000, 2025). "While EGFR inhibitors have shown efficacy in treating certain cancers, such as EGFR-mutated non-small cell lung cancer (NSCLC), their effectiveness in HGGs has been disappointing." (PMID 40113789, 2025). "Increasing evidence suggests that acquired resistance to EGFR-TKIs is associated with an enhanced cancer stem cell (CSC) phenotype." (PMID 40533443, 2025). "For instance, anti-EGFR antibodies can be conjugated to exosome surfaces to target EGFR-mutated cancers that have developed resistance to TKIs." (PMID 40843170, 2025). "The ADC LR004-VC-MMAE demonstrated potent antitumor activity by suppressing EGFR signaling and downregulating cancer stemness-associated genes, suggesting its potential as a therapeutic candidate for EGFR-positive triple-negative BC." (PMID 41007788, 2025). "EGFR is frequently overexpressed or mutated in various cancers and is activated by inflammatory mediators such as TNF-α and IL-1β." (PMID 40508016, 2025). "Cancer progression and growth are closely associated with the activation of intracellular signaling pathways mediated by EGFR, which is overexpressed in up to 60% of NSCLC cases." (PMID 41154639, 2025). "TKIs, such as Lapatinib (targeting HER2 and EGFR) and Osimertinib (targeting EGFR), are used in cancers with specific mutations." (PMID 40061961, 2025). "After TKI withdrawal, clonal EGFR mutations on extrachromosomal DNA resurfaced, demonstrating a powerful cancer cell strategy to evade drug toxicity." (PMID 40332381, 2025). "The upregulation or mutation of LAPTM4B and EGFR in a variety of cancers has attracted much attention because of their association with cancer cell proliferation, survival, drug resistance, and poor prognosis." (PMID 40231269, 2025). "Different mutations of EGFR can lead to cancer heterogeneity, with the most common mutation being the epidermal growth factor receptor variant III (EGFRvIII)." (PMID 40527884, 2025). "Overexpression of EGFR, resulting from EGFR gene amplification and/or mutations, has been detected in a variety of human cancers, including over 60% of NSCLC." (PMID 39995659, 2025). "EGFR TKIs lead to immunogenic apoptosis of cancer cells and cause the release of neoantigens, which can recruit T cell antigen presentation." (PMID 40647497, 2025). "High-resolution ctDNA phylogenetic analyses revealed that the cancer subclone which had lost the EGFR ex19del variant emerged before vaccination and continued to expand during osimertinib and vaccine exposure." (PMID 39972134, 2025). "Understanding the molecular mechanisms by which EGFR is activated, and how specific mutations modulate this activation, remains a fundamental goal in cancer biology with direct implications for precision oncology." (PMID 40650000, 2025). "Aberrant activationof EGFR signaling is commonly observed in various cancers due to mutationsin the EGFR gene or gene amplification." (PMID 39829567, 2025). "Nevertheless, our study provides several avenues worthy of further investigation, including the role of EGFR in East Asian populations with cancer and the association between ancestry and somatic mutations across multiple genes in the same pathway." (PMID 41162424, 2025). "An example would be in cancer, where genetic mutations or expression patterns such as EGFR or HER2 are involved in facilitating the identification of patients most likely to benefit from targeted therapies or immunotherapies." (PMID 40141854, 2025). "Specifically, gene set enrichment analysis indicated significant enrichment of EGFR- and cancer-associated pathways in USP11-upregulated CRC samples, highlighting USP11’s involvement in EGFR signaling." (PMID 41419456, 2025).